IL2 (interleukin 2)
Diseases named in the same sentence as IL2 in open-access papers (continued):
Sharing a sentence is not in itself a finding about the gene and the disease.
tumor (continued). "Interestingly, the dominant TCRβ specific to TRIM26G497W neo-epitope that we detected in sorted PBLs, was also detected in whole tumor RNA, but was undetectable among more than 1900 distinct clonotypes identified within 1 million reads obtained from five millions IL-2-expanded TILs." (PMID 29545564, 2018). "Importantly, recent results from tumor-targeting IL-2 immunocytokines composed of variant forms of IL-2 lacking vascular effects and low or absent Treg cell stimulation have shown promising new avenues for IL-2 applications." (PMID 30619269, 2018). "Therefore, we next examined whether IL-2/anti-CD40 was effective in young vs. elderly AE17 tumor-bearing mice and whether macrophages contributed to the efficacy of IL-2/anti-CD40 immunotherapy." (PMID 30459812, 2018). "Indeed, the data show that when IL-2/IL-12-activated NK cells were switched into glutamine-deficient conditions, metabolic rates of OXPHOS and glycolysis decreased dramatically and IFNγ production and tumour cytotoxicity was substantially inhibited." (PMID 29904050, 2018). "IL-2/CD40 slowed tumor growth in both age groups (completely in young, partially in elderly) and this may be explained by our observations that IL-2/CD40 induced several common effects on tumor-infiltrating CD11c+ cells, CD8+ T cells, and CD4+ T cells from both age groups." (PMID 30560130, 2018). "IL-2 has important functions in the tumour microenvironment, and ATRA may affect its production." (PMID 29184163, 2017). "In this study, the reasons for the association with serum CRP levels and the efficacy of nivolumab remain unclear, but serum CRP and IL-6 levels have previously been shown to predict tumor response and survival to immunotherapy, such as high dose IL-2, IFN alpha, and ipilimumab." (PMID 29262550, 2017). "Alternatively, the facts that antitumor CTL rely on IL-2 and IFNγ for tumor rejection and that pancreatic HNT CD4+ T cells were able here to secrete IFNγ and IL-2 in response to antigen suggest that these cytokines may be involved in providing help to clone 4 CD8+ T cells." (PMID 29403481, 2017). "Thus, expanding Vγ2Vδ2 T cells with pulse zoledronate stimulation and either IL-18/IL-2, IL-21/IL-15, or IL-21/IL-2 could increase their anti-tumor immunity." (PMID 28239463, 2017). "In addition, APS inhibit the tumor cell growth in Kunming mice with Ehrlich's ascites carcinoma, decrease Bcl-2 and CDK4 levels, increase the percentage of CD3+ and CD4+ T-lymphocytes, the ratio of CD4+/CD8+ T cells and the expression of IL-2/IL-2R in spleen and Bax in tumor tissue." (PMID 29344421, 2017). "However, these CAR-T cells could not produce enough interleukin-2 (IL-2), so in order to kill tumor cells it was necessary to administer exogenous IL-2." (PMID 28652918, 2017). "Interestingly, metformin, another well-known anti-diabetic drug, showed similar antitumor effect through inducing the number of CD8+ tumor-infiltrating lymphocytes (TILs) and protected them from apoptosis and exhaustion characterized by decreased production of IL-2, TNF-α, and IFN-γ17." (PMID 28496193, 2017). "It is not yet clear whether this approach will provide an increased number of responders, although the suggestion of response in patients with more aggressive tumors with anti-PD-L1 therapy is perhaps evidence that HD IL-2 and PD-1 pathway blockade may have some complementary anti-tumor efficacy." (PMID 27891227, 2016). "Tumour-selective delivery of IL-2 could potentially negate this problem." (PMID 27367731, 2016). "Also antibody-cytokine fusion proteins enhance the direct antitumour effect of the antibody and concentrate the cytokine (e.g. IL-2) in the tumour microenvironment without causing severe toxic side effects of systemic high-dose cytokine administration." (PMID 27444284, 2016). "Therefore, a 2 to 3-fold reduction in the number of Tregs at the early phase of the anti-tumour immune response could increase IL-2 availability and the pool size of effector cells." (PMID 27341421, 2016).
tumor (continued). "However, IL-2 can also expand immunosuppressive regulatory T cells (Treg) which may dampen the immune response or anti-tumor efficacy." (PMID 27660710, 2016). "Furthermore, the increased numbers of NK cells could also be due to reduced frequency of Tregs in the tumor area, as it has been shown that Tregs limit expansion of NK cells by restraining IL-2 from effector T cells." (PMID 26741508, 2016). "Next to IL-2, other γc-cytokines, such as IL-7, IL-15, and IL-21, have been described to play a role in memory T cell formation, proliferation, and survival, yet result in a lower degree of T cell differentiation but are still able to enhance anti-tumor responses." (PMID 27656185, 2016). "However, a recent study in mice using an immunocytokine of IL2-fused to tumor antigen-specific IgG in format of IgG-IL2, showed that the biodistribution and pharmacokinetics are entirely governed by the cytokine IL2 moiety, rather than the expected antibody-targeting antigen specificity." (PMID 27766096, 2016). "Therefore, IL-2 has the potential to aid in eliciting anti-tumor responses." (PMID 27669687, 2016). "Furthermore, as the bridging effect relies on both IL-2R and GM-CSFR and promotes interactions between immune and tumor cells, IL2-GMCSF may be utilized as a useful tool for dissecting specific immune responses for future clinical applications." (PMID 26850448, 2016). "It has been well documented that T cells from tumor or tumor draining lymph nodes, after activation in vitro, are effective in cancer immunotherapy and could kill tumor cells more effectively in vivo in combination with IL-2 administration." (PMID 27528023, 2016). "Based on our above observation that PD-1 was upregulated on activated T cells after being exposed to tumor cells expressing ligand PD-L1, we hypothesized that the interactions of tumor cells and activated T cells could influence the production of cytokines, such as IL-2, IFN-γ, IL-10, and TNF-α." (PMID 26361042, 2015). "Thus, the greater proportion of mature DCs and NK cells following IL-2 administration compared to GM-CSF administration could have contributed to the superior anti-tumor effects of IL-2." (PMID 26107883, 2015). "There have been attempts to deliver interleukin-2 (IL-2), interleukin-4 (IL-4) receptors, interleukin-12 (IL-12), interleukin-13 (IL-13) receptor protein, transferring-diphtheria toxin, tumor growth factor-gamma, and tumor-specific cytotoxic T lymphocytes (CTLs)." (PMID 25784614, 2015). "In addition, CD4+ T helper cells may function as effector cells either by the local production of cytokines (IFNγ and IL2) that curtail tumour growth or trigger the release of cytotoxic mediators towards MHC II tumour cells." (PMID 26081906, 2015). "Thus, constitutive expression of IL-2 in NK-92 cells through genetic modification leads to auto-activated and -proliferating cells, which reduces the manufacturing costs as well as potentially increases the in vivo tumor reactivity." (PMID 26648934, 2015). "We did not demonstrate any association between in situ tumour levels of IL-2, INF-γ or TGF-β and the pathological response elicited in the breast by NAC, highlighting the complexity and multifactorial interplay between the host defences and cancer cells in the tumour milieu." (PMID 26040463, 2015). "By targeting IL2 to the tumor microenvironment, IC might be superior at activating tumor infiltrating immune cells resulting in improved ADCC while causing less toxicity than soluble IL2." (PMID 26284063, 2015). "Immunotherapy using tumor-specific T-cells was first established by Steven Rosenberg in 1980’s and subsequently human trials of ex vivo expanded tumor-infiltrating lymphocytes (TILs) have shown promising results when combined to systemic high-dose interleukin-2 (IL-2) and lymphodepletion." (PMID 26107883, 2015).
tumor (continued). "To explore whether vaccination with TcdB-treated CT26 cells could induce type I cytokine secretion by T cells and generate tumor-specific CTLs, we examined IL-2 production, T cell proliferation, and cytolytic activities of splenocytes derived from vaccinated mice." (PMID 25340750, 2014). "Thus, IL-2 bolsters Th17 cells, which subsequently dampen host Tregs in the tumor." (PMID 24987392, 2014). "Consistent with our findings, investigators have reported that the surface expression of CD69 and NKp46 that are either up-regulated (NKp46) or induced ex-novo (CD69) after exposure to IL-2 was not inhibited by the interaction with tumor-associated fibroblasts." (PMID 25367326, 2014). "Therefore, sIL-2R/IL-2 interaction might be a significant factor with regard to tumor burden and tumor microenvironment." (PMID 24236041, 2013). "The asymptotic extremity is taken care of using a bias shift of tumour-cell distribution and guided control of drug administration, with toxicity limits enforced, during mutually-synchronized chemotherapy (as Temozolomide) and immunotherapy (Interleukin-2 and Cytotoxic T-lymphocyte)." (PMID 24369857, 2013). "Thus, it is conceivable that the combination of HD IL-2, to induce T-cell expansion, and PD-1 blockade, to eliminate tumor-induced immune suppression, might prove equally or more efficacious in select patients." (PMID 24403232, 2013). "Indeed, tumor regressions have been observed upon adoptive transfer of IL-2-expanded TIL." (PMID 23402380, 2013). "However, IL-2 may also lead to the expansion/induction of suppressive Tregs, and this can have a detrimental effect on the anti-tumor potency of the expanded TIL." (PMID 23402380, 2013). "Interestingly natural remedies like curcumin and theaflavin were found to restore IL-2 signaling, suggesting that these compounds may inhibit tumor-induced inhibition of T cell proliferation." (PMID 24053127, 2013). "Interestingly, splenocytes from tumor bearing mice showed less capacity to produce IL-2." (PMID 24213320, 2012). "Additionally, cats and dogs treated with repeated local injections of engineered histo-incompatible cells secreting high levels of human interleukin-2 (hIL-2) to the tumor site relapse less frequently and survive longer than control animals treated by surgery and radiotherapy alone." (PMID 22666387, 2012). "A recent report demonstrated that agonistic OX40 antibodies in combination with systemic IL-2 administration could generate potent anti-tumor immunity, and the synergistic nature of the combination resulted from the ability of systemic IL-2 to upregulate OX40 expression on activated T cells." (PMID 23087904, 2012). "Therefore, a strategy that can specifically deliver IL-2 to the tumor location may alleviate concerns of toxicity." (PMID 22509395, 2012). "Besides, it is questionable whether long-term IL-2 treatment is necessary for continuous tumor control." (PMID 22909342, 2012). "However, the level of IL-2 was reduced when DCs were pulsed with tumor lysate." (PMID 19001481, 2011). "Mononuclear cells infiltrating the CaPo13 tumor specimen were thawed and part of them immediately processed for RNA extraction (primary TILs), while a part was expanded in vitro by culturing for 10 days in the presence of IL-2 (20 IU/ml) and either irradiated CaPo13 cells or anti-CD3 mAb." (PMID 20711505, 2010). "To determine if a similar enhancement of therapy could be achieved with lower doses of IL-2, we treated tumor-bearing mice with Tri-mAb in combination with low dose (10,000 IU) or medium dose (50,000 IU) or high dose (100,000 IU) IL-2 daily for 5 days and monitored survival." (PMID 20426873, 2010). "However, with the potential for directly targeting chicken IL-2, the downregulation of miR-26a in these tumor cells could relieve the inhibitory effect on IL-2 expression assisting in the proliferative features of the transformed lymphocyte lines." (PMID 20441582, 2010).
tumor (continued). "Similarly, IL-2 has been described as contributing to both pro- and anti-tumor immunity." (PMID 20184734, 2010). "However, IL-2 has also been demonstrated to play a role in the expansion of regulatory T cells, and it would be of interest in future studies to determine the effect of IL-2 on regulatory T cell numbers and function in this tumor model." (PMID 20426873, 2010). "Therefore, GD2 represents a target for the potential delivery of IL2 to the tumor site." (PMID 19640287, 2009). "However, Liu and colleagues have suggested that Tex could inhibit NK cells through the blockade of IL-2 mediated NK cell activation leading to tumor escape." (PMID 19319200, 2009). "Binding of IL-2 to IL-2R on tumour cells may down-regulate surface expression of IL-2R, the intercellular adhesion molecule-I (ICAM-I) and the MHC class I antigens and may inhibit the in vitro growth of tumour cells by arresting these cells in the G0/G1 cell cycle." (PMID 19689792, 2009). "Although there is evidence that tumor cells constitutively express and secrete chemokines that can attract macrophages, we did not observe macrophages around the D5 pulmonary metastases in untreated animals with established pulmonary metastases or in animals treated with IL-2." (PMID 18001476, 2007). "In this study, we have compared the potential of IL-2- and IL-12-transfected murine syngeneic fibroblasts with IL-2- and IL-12-transfected tumour cells to generate an immune response in mice with an established tumour burden, and to establish protective immunity from tumour rechallenge." (PMID 17595664, 2007). "Indeed, the present assessment of the oxidative stress hypothesis in blood and tumour tissue is the first to establish a biological rationale – in humans – for the use of histamine in conjunction with IL-2 despite several clinical trials." (PMID 16434984, 2006). "As previously demonstrated, CD8+ cells synchronously cultured in the presence of IL-2 plus IL-7 for 50 days and expanded to 108-fold demonstrated minimal efficacy against subcutaneous tumors (P = 0.39 versus control) with 1/5 mice achieving complete tumor regression." (PMID 15566571, 2004). "Neither IL-2 nor histamine alone caused any detectable effects on tumour growth." (PMID 10952789, 2000). "Thus, CTLs generated by FN might have both killer and helper functions, since they could lyse autologous tumour cells and secrete various cytokines, including IL-2." (PMID 8932341, 1996). "In vitro killing activity of TIL populations stimulated with IL-2 and GM-CSF remained unspecific, but lysis of the autologous tumour targets as well as the allogeneic renal tumour targets was significantly enhanced (+138%) as compared with the corresponding control TILs stimulated with IL-2 alone." (PMID 7599037, 1995). "CD4+ helper T-cells, particularly T helper type 1 (Th1) polarized populations, augment tumor-restraining responses by producing IFN-γ and IL-2, and by supporting cytotoxic priming." (PMID 41562715, 2026). "TIL therapy relies on the ex vivo expansion of polyclonal, tumour-resident lymphocytes obtained from resected tumour tissue, followed by lymphodepletion of the patient and reinfusion of the expanded TIL product (often with systemic interleukin-2 support)." (PMID 41601679, 2026). "Pharmacological CD39 blockade with POM-1, when combined with IL-2cx treatment to redirect IL-2 activity, enhanced the accumulation of pre-exhausted CD8+ T cells with cytotoxic potential, thereby improving tumor control." (PMID 41668741, 2026). "In tumor-bearing mice, antitumor efficacy, serum cytokines (TNF-α, IFN-γ, IL-6, IL-2, IL-10), and hematological indices were evaluated." (PMID 41965546, 2026). "Furthermore, the combination of IL-2 immunocytokines with checkpoint inhibitors, chemotherapy, radiotherapy, and anti-angiogenic agents has elicited robust anti-tumor responses in both preclinical and early clinical trials, effectively improving tumor clearance while minimizing toxicity." (PMID 39852848, 2025).
tumor (continued). "In response to interleukin-2 (IL-2) stimulation, NK3 cells differentiate into adherent NK (A-NK) cells, which exhibit potent anti-tumor activity." (PMID 41907300, 2025). "IL-2 and IFN-γ particularly emerge as the principal elements within the IL-2-IFN-γ-NKC immune regulatory network, collaboratively activating cellular immunity and promoting tumor cell apoptosis." (PMID 39950088, 2025). "For instance, the JAK-STAT pathway is related to the inflammatory response mediated by cytokines like IL-2, IL-15, and IFN, and its excessive activation can promote tumor development." (PMID 41471272, 2025). "Tregs can produce the immunosuppressive cytokines IL-10 and TGF-β to deplete IL-2, constituting the CD3+CD4+ subpopulation to suppress the activity of effector T cells and effective anti-tumor immune response." (PMID 40703522, 2025). "Through genetic engineering, researchers have developed various L19-based immunocytokines to deliver cytokines such as IL-2, TNF, and IL-12 and studied their biodistribution in tumor-bearing mice after systemic administration." (PMID 40557148, 2025). "Collectively, the IL-2/STAT5 axis plays an indispensable role in modulating lymphocyte fate and function, significantly influencing the tumor immune microenvironment." (PMID 40698080, 2025). "On the one hand, TGF-β can directly inhibit the growth of tumor cells, while IFN-γ, IL-2, IL-12 and IL-15 enhance the cytotoxicity of lymphocytes or bone marrow cells to suppress the proliferation of tumor cells." (PMID 41333471, 2025). "It was found that T cells activated by tumor spheroids exhibited higher CD107a and IFN-γ expression than those activated by IL-2." (PMID 40123996, 2025). "Mechanistically, APS co-administration enhanced CD8+ T-cell infiltration, increased splenic and thymic indices, modulated cytokine profiles (TNF-α, IL-2, IFN-γ, IL-12, IL-6, IL-10), and reduced PD-1/PD-L1 expression in tumor tissue." (PMID 41487528, 2025). "In co-culture assays, it enhanced T cell-dependent tumor killing and restored the expression of key cytokines (GZMB, IFN-γ, IL-2, TNF-α) suppressed by tumor-derived immunosuppression." (PMID 41373467, 2025). "Through the secretion of IFN-γ, TNF-α, and IL-2, these cells enhance CD8+ T cell cytotoxicity, promote Th1 polarization, and facilitate tumor antigen presentation." (PMID 40475782, 2025). "Pro-inflammatory cytokines, such as IFN-γ, TNF-α, and IL-2, primarily secreted by CD8+ cytotoxic T cells and NK cells, are pivotal in mediating tumor-immune defense." (PMID 40868199, 2025). "LTN treatment also upregulated the secretion of key cytokines, including IL-2 and IFN-γ, further demonstrating its role in boosting CAR-T cell-mediated anti-tumor responses." (PMID 40755764, 2025). "Compared with surgical margins, tumour tissues showed a characteristic inflammatory shift, with markedly increased IL-1β and IL-6 and relatively reduced TNF-α, IFN-γ, IL-12 and IL-2." (PMID 41465261, 2025). "Ablation of NR2F6 enhances the expression of interleukin-2 (IL-2), interferon -γ (IFN-γ), and tumor necrosis factor-α (TNF-α) secretion, thereby promoting anti-tumor immune responses." (PMID 40424451, 2025). "For tumor-specific IL-2 delivery, an anti-VEGFR2 nanobody was fused with a mutant IL-2, creating a novel immunocytokine that retained antigen-selective targeting, activated peripheral blood mononuclear cells (PBMCs), and extended IL-2 half-life." (PMID 40474230, 2025). "For example, cytokines and immune modulators, including IL-2 and IFN-α, synergized with VSV to enhance both direct tumor cell killing and subsequent antitumor immune responses." (PMID 41294689, 2025). "Our data demonstrate that T cells from CAR-M-cured mice mounted robust tumor-specific responses upon re-exposure to tumor cells, characterized by rapid activation (CD69), proliferation, and effector cytokine (IL-2, IFN-γ) production." (PMID 41388305, 2025).